RNU1-130P (RNA, U1 small nuclear 130, pseudogene)
Gene: Small nuclear RNA gene on chromosome 1 (96,225,901 to 96,226,060, forward strand). Ensembl gene ENSG00000200800.
Homologues: Orthologues: chimpanzee U1 (99% identical), macaque U1 (92% identical), dog U1 (74% identical), mouse Gm23741 (71% identical), rat U1 (70% identical), rat U1 (63% identical), mouse Gm56146 (62% identical), mouse Gm23021 (61% identical), rat U1 (41% identical). Paralogues in human: RNU1-1 (82% identical), RNU1-2 (82% identical), RNU1-27P (82% identical), RNU1-28P (82% identical), RNU1-3 (82% identical), RNU1-4 (82% identical), RNVU1-18 (82% identical), RNVU1-29 (82% identical), U1 (82% identical), RNU1-89P (82% identical), RNVU1-28 (82% identical), RNVU1-7 (82% identical), and 134 more.